NOX1 (NADPH oxidase 1)
Diseases named in the same sentence as NOX1 in open-access papers (continued):
Sharing a sentence is not in itself a finding about the gene and the disease.
atherosclerosis (continued). "Among these, NOX1 plays a pivotal role in diabetes-driven atherosclerosis." (PMID 40076813, 2025). "Furthermore, the KLF4 reduction promoted by angiopoietin-like 4 (ANGPTL4)-transforming necrosis factor alpha (TNFα)-NADPH oxidase 1 (NOX1) axis plays a role in the protective effect of the anti-inflammatory ANGPTL4 protein in atherosclerosis." (PMID 38952543, 2024). "The detrimental effects of Nox1 activity may be averted by the knockout of NoxO1, which has been demonstrated to safeguard female mice from atherosclerosis and to promote longevity in mice." (PMID 39334772, 2024). "Moreover, in an atherosclerosis mouse model, Nox1 and KLF4 were significantly downregulated in the ANGPTL4 group." (PMID 36782020, 2023). "We cannot rule out a role for another Nox isoform, e.g., Nox1 or Nox2, but the possibility exists that ROS formation in atherosclerosis is not causal but downstream or an epiphenomenon." (PMID 35798762, 2022). "Several recent studies have shown that HDAC inhibition with SAHA, trichostatin A, or valproic acid, reduced ROS production in experimental diabetes, pulmonary hypertension, and atherosclerosis, through inhibitions of NOX1/2/4/5 expression via epigenetically regulating chromatin accessibility." (PMID 34667186, 2021). "Thus, the study suggests, Nox1-dependent oxidative stress is a promising target for diabetic vasculopathy, including atherosclerosis." (PMID 34571964, 2021). "In addition, in a murine model of atherosclerosis, deletion of NOX1 had a profound anti-atherosclerotic effect." (PMID 34571964, 2021). "However, in experimental murine model of diabetes, Nox1 appears to be most deleterious in the pathogenesis of atherosclerosis, whereas, Nox4 has been demonstrated to be atheroprotective." (PMID 34829831, 2021). "The uncontrolled production of ROS is directly linked to vascular damage and NOX proteins to ROS generation in the cardiovascular system: in mice, NOX1 and NOX4 isoforms are largely implicated in diabetic disease and atherosclerosis, and their deletion can significantly attenuate these pathologies." (PMID 32824091, 2020). "Rather, it is Nox1 that appears to be most deleterious in the pathogenesis of atherosclerosis." (PMID 33396868, 2020). "Nox1, but not Nox4, seems to be important in atherosclerosis in diabetes, as we demonstrated in Nox1-deficient mice on the atherosclerosis-prone ApoE−/− background made diabetic with streptozotocin." (PMID 29459239, 2018). "Additionally, the lesions in the aortic sinus appear to be more unstable implying that Nox1 has a protective role in atherosclerosis." (PMID 28688452, 2017). "NOX1/2 are mostly influential in young mice, and inhibition by the deletion of p47phox in ApoE−/− mice reduced ROS levels and attenuated the development of atherosclerosis." (PMID 28230726, 2017). "However, in cardiovascular disease such as atherosclerosis, endothelial expression of Nox2, and to a lesser extent of Nox1, appears to be enhanced, resulting in excessive superoxide generation—especially in the extracellular compartment." (PMID 29135921, 2017). "Indeed, with the use of transgenic and knockout mice Nox1 and 2 were shown to play an important role in atherosclerosis." (PMID 28688452, 2017). "Reduced formation of H2O2 was associated with increased Nox2 expression in atherosclerosis, but not with Nox1 expression." (PMID 27435231, 2016). "Moreover, and most relevantly, genetic ablation of Nox1 was shown to greatly reduce the extent of diet-induced atherosclerosis in ApoE-null mice." (PMID 24587793, 2014). "In summary, excessive ROS production by Ang II-stimulated NOX1 activation induces inflammation, accumulation of senescent VSMCs, and abnormal angiogenesis, contributing to aging and to diseases prominent in the elderly, e.g., HT, atherosclerosis, diabetes, frailty, and CVDs." (PMID 39459569, 2024).
atherosclerosis (continued). "ROS, which is formed due to the reaction in which NOX-1 plays a role, has essential contributions to physiological conditions such as angiogenesis, cell signaling, cell growth, and pathological conditions such as atherosclerosis, neurological disorders, and inflammation." (PMID 37885998, 2023). "Indeed, targeting the source of ROS producing enzyme such as NOX1 in diabetic ApoEKO mouse showed attenuated inflammation and atherosclerosis via reduction in ROS formation, suggesting the role for oxidative stress in atherosclerosis." (PMID 34829831, 2021). "Many Hei29 genes were annotated related to cardiovascular and cerebrovascular diseases, including 17 proteins such as NOX1, HSP90, AMPK, GST, and p38 in fluid shear stress and atherosclerosis." (PMID 39997416, 2025). "The epidermal growth factor receptor (EGFR), an important target of NOX1, upregulates ATF-1-mediated NOX1 expression levels and regulates cell proliferation and migration, promoting atherosclerosis progression." (PMID 36407440, 2022). "There are 7 kinds of NOX homologues that have been confirmed in humans, namely, membrane subunits NOX1-5 and DUOX1-2 (Dual Oxidase 1-2), which has been discussed for their roles in atherosclerosis." (PMID 35047104, 2022). "NOX1, NOX2, NOX4, and NOX5 appear to be of particular interest for atherosclerosis, but, unfortunately, data which demonstrate the particular functions and their mechanisms are disparate." (PMID 32664404, 2020). "Given that NoxO1 is an essential factor for Nox1-dependent ROS production, the present study to some extent supports a role for Nox1 in atherosclerosis development, although to our knowledge no gender bias has been reported for Nox1 so far." (PMID 32949971, 2020). "The role of Nox1 in atherosclerosis is not fully elucidated and there are contradictory data from studies on Nox1 depletion." (PMID 28688452, 2017). "Therefore, it is reasonable to expect that Nox1/PAK1 may contribute to the initiation and progression of atherosclerosis." (PMID 39721498, 2025). "In the vasculature, NOX1, NOX2 and NOX4 are the isoforms predominantly expressed by different cell types in the intima, media and adventitia layers and may contribute to oxidative stress in both human and experimental atherosclerosis." (PMID 32824091, 2020). "However, the data available so far are controversial and do not allow making any strong suggestions about the role of NOX1 in atherosclerosis development." (PMID 32664404, 2020).
colon carcinoma (52 papers, 2010 to 2025). "NOX1 is highly expressed in the colon and NOX1-derived ROS has been implicated in development of colon cancer by mechanisms involving enhanced tumor cell proliferation and metastasis." (PMID 36670929, 2022). "In patients with ulcerative colitis, who are at increased risk of developing colon cancer, the expression of NOX1 is significantly enhanced in the presence of active inflammation." (PMID 28330872, 2017). "It is also reported that K-Ras mutation correlates with increased NOX1 mRNA expression and colon tumor phenotype." (PMID 26116564, 2015). "According to previous studies, one of these factors could be KRAS, as its activating mutations were shown to correlate with NOX1 overexpression in human colon cancer samples and in cancer cells." (PMID 29915721, 2018). "TLR signaling also regulates colon cancer stem cell (CSC) proliferation through the NADPH oxidase 1 (NOX1)-dependent redox epidermal growth factor receptor (EGFR) signaling pathway." (PMID 39867908, 2024). "NOX1 expression levels were statistically significantly increased in the colon tumors of the CC mice when compared to their healthy counterparts (H-Cd: p < 0.05)." (PMID 38535948, 2024). "In colon cancer, an increase in ROS levels due to elevated expression of NOX1, induced by NF-kB activation, contributes to the adhesive capacity of tumor cells." (PMID 39696702, 2024). "The activation of NOX1 in colon cancer is mediated by the SRC-dependent phosphorylation of Tks4 and Tks5, which interacts with NoxA1." (PMID 39696702, 2024). "In colon cancer, the presence of the NOX1 protein in invadopodia has been observed, and its inhibition impair invadopodia formation, suggesting that NOX1 and ROS production are essential for the formation of the invasive phenotype in these cancer cells." (PMID 39696702, 2024). "Among the seven members of the NOX family, NOX1 regulates the stemness, growth, and apoptosis of colon cancer cells via several mechanisms including the regulation of several oncogenes, chemokines, and angiogenic factors." (PMID 39125413, 2024). "In colon cancer cells, S100a9 is oxidized by NOX1-produced ROS, which facilitates binding to mTORC1 and its activation." (PMID 37723445, 2023). "In colon cancer progression, S100a9 is oxidized by NOX1-produced ROS, which facilitates binding to mTORC1 and its activation." (PMID 37723445, 2023). "In support of this, knockdown of Nox1, the catalytic subunit of NOX1, in HT-29 human colon carcinoma cells diminished tumor growth and blood vessel formation, as measured by blood vessel density and vessel diameter." (PMID 35741081, 2022). "NOX1 is also expressed in colon tissues and has been implicated in pathophysiology of colon cancer and blocking of the epidermal growth factor receptor/PI3K/Akt signaling pathway reduced NOX1-induced ROS." (PMID 36670929, 2022). "In conclusion, these experiments have demonstrated that several iodonium class molecules can inhibit NOX1 activity and expression in human colon cancer cell lines." (PMID 34829628, 2021). "Our data demonstrated the interaction between NOX1 and BRAF mutation plays an important role in colon cancer." (PMID 34073365, 2021). "Another study suggested that NOX1 (over)expression was correlated with KRAS mutations (G12Cys, G12Asp, G13Asp, G12Val, G60Gly, Q61Lys, Q61His) in human colon tumors and in KRASG12V transgenic mice in the intestine compared to adjacent normal colon tissue." (PMID 33691728, 2021). "We first evaluated the ability of three colon cancer cell lines to generate ROS based on their expression of the components of the NOX1 complex." (PMID 34829628, 2021). "To evaluate the relevance of NOX1 expression for the growth of colonic cancers, we examined the effect of stable genetic knockdown of NOX1 expression on human colon cancer cells both in vitro and in vivo." (PMID 34829628, 2021).
colon carcinoma (continued). "Based on these results, NOX1 appears to be an authentic molecular target that is a suitable focus for the development of small molecule therapeutic agents to treat colon cancer." (PMID 34829628, 2021). "Because the goal of these studies was to examine the effects of a series of iodonium analogs on NOX1, we evaluated the baseline expression of each component of the NOX1 complex in three different human colon cancer cell lines." (PMID 34829628, 2021). "Our validated NOX1 mAb was then employed to assess the expression level of NOX1 protein in a panel of 7 human colon cancer cell lines, as well as in the HEK293-NOX1 stable overexpressing clone and HEK293-vector control cells." (PMID 32428030, 2020). "This study constitutes the most comprehensive histopathological characterization of NOX1 to date in cellular models of colon cancer and in normal and malignant human tissues using a thoroughly evaluated monoclonal antibody." (PMID 32428030, 2020). "We clearly demonstrate high levels of NOX1 protein expression in more than a third of colon cancers and colonic polyps compared to normal colonic tissues." (PMID 32428030, 2020). "Because our NOX1 mAb was evaluated by Western blot analysis, confocal microscopy, flow cytometry, and immunohistochemical (IHC) staining, these studies allowed the identification of relevant cellular models of colon cancer in which to study NOX1 biology." (PMID 32428030, 2020). "To develop model systems for examination of NOX1 functionality in colon cancer, we evaluated the range of NOX1 mRNA expression across a panel of 30 human CRC cell lines." (PMID 32428030, 2020). "NoxA1 regulates activation of Nox1, which can generate ROS and is expressed at high levels in colon cancer cells." (PMID 31412082, 2019). "It was shown that NOX1 supported the proliferations of colon cancer cells by regulating ROS-dependent signal pathways." (PMID 31551769, 2019). "Small hairpin RNA-mediated NOX1 silencing suppresses tumor growth in mouse models of colon cancer, and inhibition of NOX activity with pharmacological pan-NOX inhibitors decreases cancer cell proliferation without inducing apoptosis." (PMID 31249132, 2019). "The NOX1 isoform is up-regulated in colon cancer, and its overexpression correlates with inflammation rather than tumorigenesis." (PMID 31249132, 2019). "IL-4 and IL-13 increased the expression of NADPH oxidase 1 in human colon cancer cell lines, which led to the production of reactive oxygen species and cellular proliferation." (PMID 29922293, 2018). "Similar experiments utilizing IL-4-treated DLD-1 colon cancer cells confirmed the plasma membrane location of the NOX1 that had been produced." (PMID 28498822, 2017). "Of particular relevance to colon cancer growth control is the finding of decreased blood vessel density in the HT-29 xenografts from NOX1 knockdown cells." (PMID 28330872, 2017). "In this study, we have attempted to define the role of NOX1 expression in the control of HT-29 human colon cancer cell growth." (PMID 28330872, 2017). "In a previous study, transient knockdown of NOX1 expression with siRNA was shown to produce a modest effect on cell proliferation in HT-29 cells and evidence of enhanced apoptosis in Caco2 human colon cancer cells in vitro." (PMID 28330872, 2017). "Human colon cancers express higher levels of NADPH oxidase 1 [NOX1] than adjacent normal epithelium." (PMID 28498822, 2017). "Our laboratory recently demonstrated that small molecule inhibitors of NOX1 decrease human colon cancer cell proliferation both in vitro and in human tumor xenografts." (PMID 28498822, 2017). "In related experiments, NOX1 expression was decreased by over 80% following transient expression of NOX1 siRNA in Caco2 human colon cancer cells." (PMID 28330872, 2017).
colon carcinoma (continued). "The relationship between IL-4Rα and NOX1 in these tumors and adjacent normal tissues suggests that the conditions exist in the clinic to support a mechanistic relationship between IL-4 and colon cancer proliferation." (PMID 28498822, 2017). "Decreased steady-state MAPK phosphorylation occurred concomitant with a significant increase in protein phosphatase activity for two colon cancer cell lines in which NOX1 expression was knocked down by RNAi." (PMID 28330872, 2017). "In human colon cancers and adjacent normal tissues, the expression of NOX1 and the Type II IL-4R are significantly correlated." (PMID 28498822, 2017). "To investigate the role that NOX1 plays in colon cancer growth, we used shRNA to decrease NOX1 expression stably in HT-29 human colon cancer cells." (PMID 28330872, 2017). "NOX1 expression was increased 4- to 5-fold in a time- and concentration-dependent manner by both cytokines in human colon cancer cell lines when a functional Type II IL-4 receptor was present." (PMID 28498822, 2017). "Based on the conclusion that all components of the NOX1 complex are overexpressed in human colon cancer, we focused our current studies on an examination of the role of NOX1 in colon cancer growth in cell culture and in vivo." (PMID 28330872, 2017). "NOX1, originally discovered utilizing Caco2 human colon cancer cells, is expressed in both normal and malignant colonic tissue and at lower levels in vascular smooth muscle, uterus, prostate, and osteoclasts." (PMID 28330872, 2017). "Our prior results demonstrated that NOXO1 and NOXA1, in addition to NOX1, are also increased in clinical colon cancer specimens, facilitating the potential for active NOX1 activity." (PMID 28498822, 2017). "It is appropriate, however, to point out limitations in our understanding of the role of NOX1 in the control of colon cancer growth." (PMID 28330872, 2017). "Previous work has demonstrated that inhibition of NOX1 significantly interferes with α2β1-integrin signaling as well as the migration of colon cancer cells on collagen." (PMID 28330872, 2017). "Taken together, these data provide evidence demonstrating that IL-4 and IL-13 upregulate NOX1 in colon cancer cells though the IL-4R/STAT6 pathway, and that GATA3 plays an important role in the transcriptional regulation of NOX1." (PMID 28498822, 2017). "In concert with these results, we found that IL-4 increased NOX1 expression in other colon cancer lines, including DLD-1, WiDr, NCI-H508, and SW403 cells." (PMID 28498822, 2017). "Our current results showing that NOX1 expression is diminished as colon cancer cells undergo invasive phenotype change also support such suggestion." (PMID 26116564, 2015). "Molecular switch from NOX1 to NOX2 in colon cancer cells induces ROS production and subsequently enhances MMP-7 expression by deactivating AMPK, which otherwise inhibits stimulus-induced autoregulation of ROS and NOX2 gene expression." (PMID 26116564, 2015). "MMP-7 overexpression drives colon cancer cells into an highly invasive phenotype through molecular switch from NOX1 to NOX2." (PMID 26116564, 2015). "High expression of NOX1 is observed during colon cancer, and ROS act as signaling molecules in migration and invasion of cancer cells." (PMID 26116564, 2015). "We next examined which NOX isoform is responsible for ROS production in colon cancer cells, which reportedly express a high level of NOX1 and moderate level of NOX2." (PMID 26116564, 2015). "NOX isoforms were differentially expressed between less metastatic (HT29 and Caco2) and highly metastatic (SW620 and HCT116) colon cancer cells, as shown in copy number measurement of NOX1 and NOX2 mRNA." (PMID 26116564, 2015). "O'Leary and coworkers even described increased metastatic potential of colon cancer cells upon LPS stimulation via Nox1-mediated redox signaling." (PMID 24371445, 2013). "Nox1 was found in invadopodia in human colon cancer cells, and its inhibition disrupted invadopodia formation." (PMID 22873355, 2012).